FZD1 (frizzled class receptor 1)
Diseases named in the same sentence as FZD1 in open-access papers (continued):
Sharing a sentence is not in itself a finding about the gene and the disease.
cancer (28 papers, 2012 to 2025). A tumor composed of atypical neoplastic, often pleomorphic cells that invade other tissues. "The results of ChIP-seq showed that YB-1 maintained the stemness of cancer stem cells by promoting the expressions of stemness-associated genes (FZD-1, p21, GLP-1, GINS1, and Notch2)." (PMID 31375149, 2019). "In the subsets of fibroblasts, cancer-associated fibroblasts (CAFs) specifically express oncogenes such as NT5E and FZD1." (PMID 36460803, 2023). "In 419 total unique analyses, 45 analyses showed that the mRNA expression level of FZD1 was significantly different between cancer tissue and paracancerous tissue, consisting of 20 up-regulated expression and 25 down-regulated expression." (PMID 33618667, 2021). "According to the published data, GINS1, p21, GLP-1, Notch2, and FZD-1 play important roles in the stemness of cancer stem cells." (PMID 31375149, 2019). "The Notch2 and FZD-1 proteins, important members of the Notch and Wnt signaling pathways, respectively, in cancer stem cells, play important roles in the proliferation and stemness maintenance of cancer stem cells." (PMID 31375149, 2019). "In the present study, the results revealed that the transcription factor YB-1 could maintain the stemness of cancer stem cells by promoting the expression of stemness-related genes (FZD-1, p21, GLP-1, GINS1, and Notch2)." (PMID 31375149, 2019). "Collectively, the biological function of FZD1 could be involved in modulating the sensitivity of various human cancers to chemotherapeutic drugs." (PMID 29789460, 2018). "The WNT signaling in our study is altered by the deregulation of APC, FZD1, FZD6, LRP6, and WNT10B, which are included by KEGG in the process of cancer proliferation." (PMID 34715892, 2021). "The results revealed that YB-1 knockout led to significant decreases in the promoter activities of the FZD-1, p21, GLP-1, GINS1, and Notch2 genes in cancer stem cells." (PMID 31375149, 2019). "The top-scoring genes recurring in the four gene sets included key cancer genes, KAT2A, SKP1, FZD1, JAG1 and PSEN2." (PMID 28473661, 2017). "In Proteoglycans in cancer pathway, FZD9, GPC1, PAK1, FZD1, and ACTB were extracted." (PMID 30733969, 2019). "However, rescue of YB-1 expression resulted in significant increases in the promoter activities of the FZD-1, p21, GLP-1, GINS1, and Notch2 genes in YB-1 knockout cancer stem cells." (PMID 31375149, 2019). "Genes upregulated by >1.5‐fold in cancer tissues rather than in normal intestinal mucosae include Wnt signaling‐related genes such as Fzd1 (fold change [FC], 5.6), Myc (FC, 2.6), Ccnd1 (FC, 1.6), Mmp2 (FC, 10.4), Mmp7 (FC, 16.0), Mmp8 (FC, 12.9), Mmp12 (FC, 52.2), and Spp1 (FC, 149.3)." (PMID 35274815, 2022). "While OMP-18R5, having cross-reactivity with 4 other Fzd receptors (Fzd1/2/5/8), may show broad application for a wide range of cancers, the lack of specificity towards its intended target poses concerns for its off-target effects." (PMID 33436039, 2021). "In this context, the transcription factor YB-1 could promote cancer stem cell proliferation, maintain cancer stem cell stemness, and suppress cancer stem cell apoptosis by promoting the expression of GINS1, p21, GLP-1, Notch2, and FZD-1." (PMID 31375149, 2019). "Combining our results and previous reports, it could be concluded that the transcription factor YB-1 promotes cancer stem cell proliferation, maintains cancer stem cell stemness, and suppresses cancer stem cell apoptosis by promoting the expression of GINS1, p21, GLP-1, Notch2, and FZD-1." (PMID 31375149, 2019).
brain disease (1 paper, 2024). "Among them, 8 differential urinary proteins were previously reported to be closely associated with brain disease, including NP, FZD1, B2M, EPCR, ATRN, MB, CA1and VPS4A." (PMID 38836960, 2024).
neurological disorders (1 paper, 2021). "The CpG most strongly driving this association was annotated to FZD1, a gene involved in the Wnt signaling pathway that (i) is essential for neurological development and the maintenance of the nervous system, and (ii) has been associated with susceptibility to neurological disorders." (PMID 34118639, 2021).
psychiatric disorder (1 paper, 2021). A disorder characterized by behavioral and/or psychological abnormalities, often accompanied by physical symptoms. "We asked whether the apparent correlation between the age-dependent expression patterns of FZD1 and PTH2R and their dysregulation in ASD is a random observation or can be generalized to other GPCR DEs in ASD or even to other psychiatric disorders." (PMID 34831190, 2021).
FZD1 also shares sentences with these, for which no sentence is quoted: infection (3 papers); Kashin-Beck disease (2); melanoma (2); adenoma (1); cervical cancer (1); colon adenoma (1); colorectal adenocarcinoma (1); esophageal cancer (1); heart defects (1); Hepatitis (1); Hypertension (1); invasive carcinoma (1); ischemia (1); lip (1); liver fibrosis (1); lymphoma (1); major depressive disorder (1); medullary thyroid cancer (1); neurodegenerative disease (1); osteoarthritis (1); pancreatic ductal adenocarcinoma (1); Parkinson disease (1); renal carcinoma (1); renal fibrosis (1); rheumatoid arthritis (1); serous carcinoma (1); spinal cord injuries (1); Stroke (1); tubular adenoma (1); ulcerative colitis (1).
A further 1 disease shares a sentence with FZD1 in 1 paper.